IL6 (interleukin 6)
Diseases named in the same sentence as IL6 in open-access papers (continued):
Sharing a sentence is not in itself a finding about the gene and the disease.
COVID-19 (continued). "Aiming at finding discriminant oral cytokines for COVID-19 status, we employed volcano plot and VIP plot, finding out seven COVID-19-related discriminant cytokines (IL-6, IL-5, GCSF, IL-2, TNF-α, GMCSF, and INF-γ), while only one (IL-12p70) for controls." (PMID 34394024, 2021). "In severe cases of COVID-19, high levels of TNF-α, IL-1 and IL-6 are associated with coagulation activation and thrombin generation, leading to disseminated intravascular coagulation or thrombotic complications." (PMID 33916917, 2021). "Adults with severe COVID-19 have increased levels of the inflammatory interleukins (IL)-2, IL-6, IL-7, IL-10, and tumor necrosis factor-α that constitute the “cytokine storm”." (PMID 34123972, 2021). "Elevated lactate dehydrogenase, C-reactive protein, and interleukin-6 levels are other common laboratory findings among hospitalized patients with COVID-19." (PMID 34208017, 2021). "Previous studies investigated different biomarkers such as C-reactive protein (CRP), interleukin (IL)-6, procalcitonin (PCT), etc. in COVID-19 patients and their association with disease progression." (PMID 34895167, 2021). "A case series of 7 patients with severe COVID-19 treated with infliximab demonstrated a decrease in serum IL-6 levels and reduced mortality rates (35% in the control group vs. 14% in the infliximab group)." (PMID 34959657, 2021). "The most important cytokine during COVID-19 is interleukin 6 (IL-6), which is positively correlated with the severity of COVID-2019 symptoms." (PMID 34062770, 2021). "SARS-CoV-2-infected cells treated with famotidine demonstrate reduced expression levels of the inflammatory mediators CCL-2 and IL6, drivers of the cytokine release syndrome that precipitates poor outcome for patients with COVID-19." (PMID 34214498, 2021). "Cavalli and coworkers compared the effectiveness of IL-1 and IL-6 inhibition in treating COVID-19 cytokine storm syndrome." (PMID 34458380, 2021). "The severe or critical cases of COVID-19 correlate with high levels of IL6 (during the cytokine storm) and low lymphocyte counts." (PMID 33941085, 2021). "The COVID-19 (+) patient median values for pro-inflammatory markers (C-reactive protein, ferritin, fibrinogen, and IL-6) were all increased by 1.5–2.0-fold greater than that observed in COVID-19 (−) patients." (PMID 35087853, 2021). "In patients with severe COVID-19, this abundance was also associated with the presence of CD8+ T cells that produced high amounts of GM-CSF, which can further induce IL-6 production." (PMID 33643308, 2021). "The main factor of this storm in COVID-19 seems to be interleukin 6 (IL-6), which is produced by activated leukocytes." (PMID 34033288, 2021). "Of note is that a large number of studies have shown that the levels of IL-6 were significantly higher in patients with severe COVID-19 as compared to those in uncomplicated individuals." (PMID 33937333, 2021). "As detailed above, the levels of IL-2-receptor (IL-2R) and IL-6 are significantly increased in the serum of COVID-19 patients and correlate with disease severity." (PMID 33777864, 2021). "This is a chimeric monoclonal antibody that blocks IL-6 by binding to it and studies suggested that this medication holds potential for the treatment of COVID-19." (PMID 34359931, 2021). "With varying degrees of efficacy, several large-scale clinical trials have now demonstrated a reduction in the mortality rate or symptomatic improvement in COVID-19 patients by blocking IL-6 signalling." (PMID 34564316, 2021). "In agreement, multiplex cytokine analysis indicates that IL-6 is highly increased in COVID-19 patients with low FT3 serum values." (PMID 33794925, 2021). "Despite the poorly defined pathophysiology of cytokine storm, widespread acceptance of the term in COVID-19 has motivated to apply potent immunomodulatory therapies such as IL-6 inhibitors and high-dose corticosteroids." (PMID 34912345, 2021).
COVID-19 (continued). "The role of IL-6 in COVID-19 is further highlighted by the fact that elevated IL-6 levels in hospitalized COVID-19 patients predict respiratory failure and increased mortality." (PMID 33660966, 2021). "Regarding Th2 cytokines, COVID-19 patients showed higher levels of IL-6, IL-10 and IL-13, but lower levels of IL-4 (p < 0.001, for all of them)." (PMID 33718270, 2021). "Among the many stands is IL-6, whose circulating concentrations are known to be increased in many proinflammatory critical care syndromes, including COVID-19." (PMID 34768455, 2021). "As a part of the protocol, IL-6 levels are routinely measured for every patient with COVID-19 in our clinic." (PMID 34177303, 2021). "IL-1 beta (IL-1β), which is a main activator of IL-6 expression, has attracted our attention in the exploration of COVID-19 therapies." (PMID 33404925, 2021). "The finalized IL-6 nomogram highlights cytokine storm as a core mechanism for COVID-19-related death, which is further supported by the fact that nomograms incorporating cytokine indices dominated the top of the ranking in predictive value for mortality." (PMID 33693017, 2021). "In another study, T cell numbers in COVID-19 patients were negatively correlated with patient survival and with serum IL-6, IL-10, and TNF-α concentrations." (PMID 33445583, 2021). "In this study, we investigated the association between peripheral blood IL-6 levels and MAFLD at admission and risk of having more severe illness in hospitalized patients with COVID-19." (PMID 33763027, 2021). "The prognostic value of IL-6 and C-reactive protein for COVID-19 severity has already been described." (PMID 33572045, 2021). "The elevated serum levels of IL-6 in COVID-19 patients and its circulating levels are positively correlated with the severity of disease, indicating that IL-6 plays a key role in the pathogenesis of CRS." (PMID 34955842, 2021). "IL-6 was significantly higher in both severe COVID-19 ICU patients [21.3 pg/ml, 5-95% percentile; 1.94-3612 pg/ml; p=0.0014)] and in non-ICU patients [9.25 pg/ml, 5-95% percentile; 1.94-58.9 pg/ml; p=0.0135)] compared with healthy subjects." (PMID 33968010, 2021). "The most studied interleukin is perhaps IL-6, given that tocilizumab, a monoclonal antibody directed against the IL-6 receptor, can be used as therapy for COVID-19 patients who present signs of hyperinflammation." (PMID 34457119, 2021). "Patients with severe COVID-19 have higher serum concentration of IL-6, IL-10, IL-2 and IFN-γ, higher numbers of neutrophils in the peripheral blood and reduced counts of T cells (particularly CD8+ T cells) compared with patients with mild disease." (PMID 33906375, 2021). "In COVID-19 patients, IL-1β, IL-6, IL-8, IL-17A, IP-10, and MCP-1 levels differed significantly from the healthy control group." (PMID 34047654, 2021). "HMGB1 triggers toll-like receptor-4, generating the release of pro-inflammatory cytokine including IL-6, which is one of pathophysiological hallmarks of the cytokine storm in critically ill COVID-19 patients." (PMID 33939645, 2021). "Among the proinflammatory cytokines (IL-1β, TNF-α, IL-8, and IL-6) analyzed herein, TNF-α was seen as a risk factor for the death of patients with severe or critical COVID-19." (PMID 34725309, 2021). "A key characteristic of severe COVID-19 is the dysregulation of inflammatory pathways with the increased production of cytokines such as interleukine-6 (IL-6) and tumor necrosis factor-α (TNF-α)." (PMID 34960708, 2021). "IL1B mRNA levels were not different in the upper and lower airways of hospitalized COVID-19 patients, while IL6 transcripts appeared to be predominantly expressed in the nasopharyngeal swabs compared to the BALF." (PMID 34492226, 2021).
COVID-19 (continued). "Severely ill patients hospitalised with COVID-19 exhibit increased levels of Interleukin (IL)-1β, IL-2, IL-6, IL-7, IL-8, IL-10, IL-17, granulocyte colony stimulating factor (G-CSF), monocyte chemoattractant protein 1 (MCP-1) and tumor necrosis factor (TNF)." (PMID 34205262, 2021). "An early spike in IL-6 is observed in severe COVID-19 illness that is correlated with complement activation." (PMID 34775962, 2021). "Our analyses predicted that individuals with severe COVID-19 also have accelerated monocyte-to-macrophage differentiation mediated by increased IL-6 and reduced type I IFN signalling." (PMID 34260666, 2021). "The pathogenesis of severe forms of COVID-19 is characterized by hyperinflammatory syndrome, i.e. a cytokine storm; with overproduction of inflammation-related molecules such as interleukin-6 (IL-6), C-reactive protein (CRP), and ferritin." (PMID 34038475, 2021). "A detailed assessment of the cytokine profile in severe cases of COVID-19 indicates that some cytokines and chemokines are strongly elevated, such as interleukin (IL)-6, IL-8, and tumor necrosis factor (TNF)." (PMID 33979301, 2021). "Nevertheless, tofacitinib, a Janus kinase inhibitor which suppresses Th1 response and IL-6 production has recently been shown to decrease mortality in patients hospitalized with COVID-19 even when the majority of patients were already given corticosteroids." (PMID 34938289, 2021). "Increases in many cytokines, especially CRP, sedimentation, ferritin, PRC, and IL-6, have been reported in COVID-19 patients." (PMID 34868686, 2021). "Due to the high level of IL-6 correlating with poor outcomes in severe COVID-19 patients, the therapeutic effect of tocilizumab in the patients with high IL-6 was further analyzed." (PMID 33731184, 2021). "In summary, several proteins in plasma that are increased in severe COVID-19 patients, such as IL-6, IL-8, IL-18, MCP-1, OPG, and HGF, are more abundant in healthy elderly compared to young individuals." (PMID 34434199, 2021). "IL-6 has been recognized as another key inflammatory marker in COVID-19 and a meta-analysis has shown elevated levels in patients with complicated COVID-19." (PMID 34276355, 2021). "In relation to COVID-19, IL-37 has been suggested to be a potential treatment based on its anti-inflammatory profile to inhibit IL-1β, IL-6 and TNF, which are the main players of the cytokine storm." (PMID 34422917, 2021). "Meta-analyses reveal associations between increased levels of cytokines (primarily interleukin-6 (IL-6)) in peripheral blood and higher disease severity and mortality in COVID-19." (PMID 34616852, 2021). "Interleukin-6 is induced during COVID-19, and there are reports of improved COVID-19 outcomes following anti-IL-6 therapy in patients with SCD." (PMID 34368185, 2021). "Several approaches such as IL-6 inhibitors and immune checkpoint inhibitors have been proposed to counteract the “cytokine storm” present in severe COVID-19 patients." (PMID 34341347, 2021). "The laboratory indicators of hypercoagulability in COVID-19 correlate with the overproduction of the inflammatory markers (interleukin-6 and -8, fibrinogen, CRP) and cells (neutrophilia and monocytosis)." (PMID 34381066, 2021). "For instance, intravenous infusion of an anti-GM-CSF mAb (Lenzilumab, 600 mg, thrice) significantly reduced blood levels of IL-1α and IL-6 in 11 out of 12 patients with severe COVID-19." (PMID 34022793, 2021). "Two meta-analyses on IL-6 and IL-10 circulating levels found a correlation between the disease severity and mortality in COVID-19 patients." (PMID 34646263, 2021). "After SARS-CoV-2 infection, vascular endothelial cells become dysfunctional and IL-6, TNF-a, and MCP-1 levels are elevated, leading to COVID-19-associated vascular inflammation and coagulopathy, particularly endotheliitis in the lungs, heart and kidney." (PMID 34344353, 2021).
COVID-19 (continued). "In vivo, a dramatic increase in IL-6-producing CD14+ /CD16+ monocytes was observed in the peripheral blood of COVID-19 patients in the intensive care unit." (PMID 34225749, 2021). "Of all the available drugs that specifically inhibit IL-6 pathway, only tocilizumab (an IL-6 receptor antagonist) has, so far, a reasonable body of evidence in COVID-19." (PMID 33679753, 2021). "IL-6, which is related to the pathogenesis of sarcopenia, plays an important role in the inflammatory storm of COVID-19." (PMID 34112103, 2021). "In view of these observational data, and the well-known central role of IL-6 in cytokine storms, tocilizumab was advocated as an adjunctive therapy in patients with severe COVID-19." (PMID 33499310, 2021). "In particular, suppressing IL-6 and IL-1 production and blocking their receptors and actions are currently attracting attention as therapeutic targets for severe COVID-19." (PMID 34684771, 2021). "used the databases to compare cytokine profiles between AOSD and COVID-19, and revealed higher IL-6 and IL-10 in severe COVID-19 than in AOSD." (PMID 34367188, 2021). "In COVID-19 patients a pro-inflammatory status with high levels of IL-6, IL-1B and TNF-α has been demonstrated." (PMID 34313585, 2021). "According to a study by Min, 308 patients with COVID-19 showed that severe cases had a higher level of proinflammatory factors at admissions such as IL-2R, IL-6, IL-8, IL-10, and TNF-α." (PMID 34970527, 2021). "Critically ill patients with COVID-19 exhibited pneumonia-like symptoms and extremely elevated serum IL-6 levels, similar to those seen in cases of HLH." (PMID 34253862, 2021). "In agreement with this, patients with severe COVID-19 presented high levels of d-dimer, serum ferritin, IL-6 and C-reactive protein." (PMID 33709775, 2021). "A few studies that reported IL-6 values in the ng/mL range in some COVID-19 patients used different analysis platforms, underscoring the importance of using appropriate control groups and analytical techniques." (PMID 33921604, 2021). "Understanding the conflicting functions of IL-6 will be necessary not only for the correct therapy for COVID-19 but also for us to live healthy and enjoyable lives." (PMID 34576053, 2021). "Additionally, results from a recent in-depth analysis of NK cells isolated from patients with COVID-19 revealed that despite low NK cell numbers in these patients, the NK cell phenotype associated with severe disease was robustly activated and associated with increased IL-6 levels." (PMID 33643308, 2021). "Nonetheless, we had adequate power to exclude the large effect sizes that have been observed in prior studies of inflammatory biomarkers such as IL-6 in COVID-19 and the Ang-Tie-2 axis in sepsis and ARDS." (PMID 33874973, 2021). "Dex treatment, a potent suppressor of systemic inflammation including IL-6, has been shown to reduce mortality in hospitalized COVID-19 patients under oxygen supplementation treatment or mechanical ventilation." (PMID 34576169, 2021). "In contrast, in patients with COVID-19 pneumonia, procalcitonin and C-reactive protein were negative predictors for COVID-19 pneumonia, whereas progranulin and interleukin-6 were positive predictors of COVID-19." (PMID 34476621, 2021). "Regarding the use of anti-IL-6 in COVID-19, a meta-analysis showed a favorable effect on mortality at 28 days after randomization." (PMID 34421600, 2021). "IL-6 and D-dimer testing provide an early sensitive and specific predictor of a severe course of COVID-19." (PMID 34065057, 2021). "It is suggested that further investigation be initiated, regarding the reliability of IL-6 as an independent and vital biomarker to detect COVID-19 disease severity." (PMID 34538093, 2021). "During 1 year of COVID-19 pandemic multiple studies evaluating the effects of IL-6 inhibitors tocilizumab and sarilumab in COVID-19 patients showed controversial and sometimes disappointing results." (PMID 34586459, 2021).
COVID-19 (continued). "This process is mediated by tumour necrosis factor-alpha (TNFα) and interleukin 6 activity.Many reports also highlighted a strong association between elevated PCT and severe COVID-19." (PMID 34855832, 2021). "In this context, high levels of IL-6 and increased concentrations of highsensitivity troponin I have been described as frequent in seriously ill COVID-19 patients." (PMID 33776561, 2021). "This agrees with demonstrations of elevated values for CRP, D-Dimer, IL-6, and ferritin in COVID-19 patients." (PMID 34510338, 2021). "Some previous studies have already explored the predictive value of IL-6 on several clinical aspects of COVID-19." (PMID 33679753, 2021). "Ten randomized controlled studies on anti-IL6 treatment in hospitalized patients with COVID-19 have been reported." (PMID 34000622, 2021). "The only single case of critical COVID-19 among children in our study, had significantly elevated IL-6 (120.31 ng/L), IL-10 (33.38 ng/L), and PCT (0.43 ng/ml), and acute respiratory distress syndrome, acute renal failure and cardiac insufficiency occurred." (PMID 33593415, 2021). "Increased serum galectin-3 in severe cases in correlation with increased concentrations of IL-6 and acute phase proteins was consistent with the cytokine storm observed in severe COVID-19." (PMID 34439802, 2021). "As expected, after TLR9 agonist CpGB stimulation the percentage of IL-6+ B cells increased in acute COVID-19 patients vs. healthy controls and convalescent patients irrespective of possible chest X-ray abnormality." (PMID 34595175, 2021). "A previous study found that the MHC-2 expression on monocytes and lymphocytes were strongly inhibited by plasma from COVID-19 patients with high IL-6 levels, supporting the notion that an overproduction of IL-6 contributes to disease progression." (PMID 34943881, 2021). "The most important sources of IL-6 reported in COVID-19 were myeloid cells, but it remained unclear which subtype of myeloid cells predominantly contributes to IL-6 production." (PMID 33692788, 2021). "Present data showed that the expression level of IL-6 is significantly increased in the PBMC of both severe COVID-19 and CD patients in comparison to controls (p < 0.0001 for both of them)." (PMID 34895167, 2021). "Our biomarker findings are similar to previously reported associations of the levels of several cytokines (e.g., IL-1ra, IL-2, IL-6, IL-8, IL-10, and IP-10) with COVID-19 severity and mortality." (PMID 34386533, 2021). "Considering the critical role of hyperinflammation in the pathophysiology of COVID-19, much attention has been paid to anti-inflammation therapy, such as corticosteroids, IL-6 blocking agents, and Janus kinase (JAK) inhibitors." (PMID 35155477, 2021). "Being critically ill and lymphocyte count, SOFA score, APACHE II score, PaO2/FiO2, IL-6, and CRP on admission were associated with poor prognosis in COVID-19 patients." (PMID 34167463, 2021). "As expected, the markers of inflammation, such as CRP, IL-6, or ferritin, were significantly higher in COVID-19 patients with pneumonia." (PMID 34680053, 2021). "Chronic inflammation and increased cytokine production, like TNF-α, IL-6, and CCL5, are critical features of COVID-19 patients, which suggests that they cause severe lung injury, multi-organ failure, and poor prognosis." (PMID 33804769, 2021). "Based on the fact that IL-6 is one of the cytokines observed during the “cytokine storm” typical of COVID-19, we measured plasma levels of IL-6." (PMID 34944747, 2021). "In analyses of the pathological mechanisms of COVID-19, critically ill patients with COVID-19 have shown significantly elevated levels of IL-6, and tocilizumab treatment was found to be beneficial in these patients." (PMID 34253862, 2021). "A recent study has linked the IL-6-mediated signaling axis with MCP-1, IL-8, and IL-10 to the elevation of PAI-1, recently shown to be elevated in COVID-19 patients." (PMID 34452463, 2021).